HSF1 (heat shock transcription factor 1)
Diseases named in the same sentence as HSF1 in open-access papers (continued):
Sharing a sentence is not in itself a finding about the gene and the disease.
cancer (continued). "A number of studies have indicated that the elevated HSF1 levels in cancer cells can modulate energy metabolism and switch glucose utilization towards the glycolytic pathway." (PMID 32331382, 2020). "Here we extend this analysis to unravel the proteomic consequences of stromal HSF1 activation, in cancer as well as in the preceding stage of inflammation." (PMID 33288768, 2020). "Although HSF1 knockdown impairs the proliferation of cancer cells, it has been reported to have only a minimal effect on the viability of non-cancer cells." (PMID 32408596, 2020). "We have previously shown that, in the context of cancer, HSF1 in fibroblasts drives the transcription of genes involved in inflammation, ECM remodeling, and wound healing." (PMID 33288768, 2020). "Taken together, the HSF1 signaling networks constitute an intricate and pivotal pro-oncogenic pathway, and HSF1 inhibitors have become a hotspot in molecular targeted cancer therapy research." (PMID 32110802, 2020). "For instance, HSF1 can drive the transcription of PDK3 (Pyruvate Dehydrogenase Kinase 3) to promote glycolysis in chemo-resistant cancer cells." (PMID 32838807, 2020). "We review what is currently known regarding the contribution of HSF1 activity to cancer pathology, its regulation and expression across human cancers, and strategies to target HSF1 for cancer therapy." (PMID 32331382, 2020). "In both cancer and non-cancer cells, HSF1 activity is also subject to the energy status of the cell." (PMID 32331382, 2020). "Several studies have shown that HSF1 also modulates the sensitivity of cultured cancer cells to a variety of cytotoxic agents." (PMID 32331382, 2020). "It has been widely reported that HSF1 is often overexpressed in cancer cells, thus suggesting that it has a role in tumorigenesis." (PMID 32457290, 2020). "When co-cultured with cancer cells, fibroblasts express an HSF1-dependent transcriptional program, which includes genes involved in wound-healing and ECM remodeling." (PMID 33288768, 2020). "Cancer cells exhibit high expression of HSF1, and in vivo sumoylation of HSF1 by SUMO1 is dependent upon phosphorylation of a specific serine residue." (PMID 32530958, 2020). "The abnormal expression and activation of HSF1 is not only closely related to poor clinical prognosis, but is also involved in a network of pro-oncogenic events, including cancer cell proliferation, survival, apoptosis resistance, and glucose metabolism." (PMID 32110802, 2020). "An important advance gained from these studies was the revelation of the extent of HSF1 transcriptomic negative regulation, as well as a cohort of HSF1 targets in cancer cells distinct to that of heat shock." (PMID 32331382, 2020). "Recently, a comparison of HSF1-CaSig in different cancer types revealed that numerous genes that are overexpressed, including HSF1, reside in a region of chromosome 8q, which is typically amplified in cancer." (PMID 32408596, 2020). "A higher number of cancer cells was found and they penetrated deeper into the matrix of WT colons versus Hsf1 null colons." (PMID 33288768, 2020). "In certain cancer types, such as multiple myeloma, FBXW7 is downregulated, which causes accumulation of HSF1 to the nucleus and subsequently prevents the attenuation of the heat shock response." (PMID 32408596, 2020). "Currently, there are several ongoing clinical trials to evaluate the potential of targeting HSF1 for cancer treatment." (PMID 32838807, 2020). "In CAFs, where HSF1 activity is high, HSF1 drives a transcriptional program that is distinct from the HSF1-CaSig in adjacent cancer cells." (PMID 32408596, 2020). "These include how the HSF1 transcriptional activation domain uncouples transcriptional pausing, the mechanism by which the regulatory domain inhibits HSF1 activity, as well as the primary factors leading to HSF1 activation in cancer cells." (PMID 32331382, 2020).
cancer (continued). "Not surprisingly, HFS1 is upregulated in many types of cancers that hijack HSF1-dependent pathways to promote their own survival and its targeting is a promising strategy to combat cancer." (PMID 31052524, 2019). "KRIBB11, a synthetic chemical and an HSF1 inhibitor, is known to have suppressive effects on heat shock response and cancer growth." (PMID 31540279, 2019). "We found that only 54.1% of all tumors have a normal predicted 8q24.3 copy number and that 8q24.3 located genes including HSF1 are mainly overexpressed due to increased copies number of 8q24.3 in different cancers." (PMID 31699156, 2019). "Intriguingly, PGC-1α also acts as a repressor of HSF1-mediated transcriptional program in hepatocytes and in cancer." (PMID 30941017, 2019). "We analyzed potential effects of E2 on activation of HSF1 using a range of established breast cell lines, i.e., two non-tumorigenic (MCF10a and MCF12a) and four originated from cancer patients (MCF7, SKBR3, MDA-MB-468, BT-547) with a different ER status." (PMID 31614463, 2019). "HSF1 promotes cancer development and progression, and increased HSF1 levels are frequently observed in multiple types of cancers." (PMID 31540279, 2019). "Here, we will discuss a subset of HSPs known to be significant in cancer, including Hsp27, Hsp70, and Hsp90, each regulated by HSF1." (PMID 31514477, 2019). "The aim of this study using an individual patient data meta-analysis approach is to assess the overall role of HSF1 expression in relation to CNA in cancer prognosis." (PMID 31699156, 2019). "Nevertheless, the origin and the interpretation of HSF1 overexpression in cancer are poorly understood since HSF1 appears to drive a distinct regulation in cancer cells." (PMID 31699156, 2019). "Regarding cancer cell defense mechanism, it has been shown that HSF1 forms a positive feedback loop with pyruvate dehydrogenase 3 (PDK3) to drive chemoresistance of cancers." (PMID 31878360, 2019). "In hepatocellular carcinoma, HSF1 reduces the anti-cancer effects of epirubicin and increases the cell viability by promoting protective autophagy through upregulation of ATG4B expression." (PMID 31878360, 2019). "When looking at the whole expression level, hierarchical clustering presented a set of genes correlated with the HSF1 expression, indicating a consistent transcriptional program involving HSF1 in different cancer types." (PMID 31699156, 2019). "Further studies in cancer cells also revealed that HSF1 directly regulates the expression of SMAC (mitochondria-derived activator of caspase) and other mitochondrial genes inhibiting mitochondrial apoptosis." (PMID 30941017, 2019). "Both FMRP and HSF1 were previously indicated to be upregulated in other cancers and the HSF1 activity in MPN was also recently reported." (PMID 31321035, 2019). "In cancer cells the protective function of HSPs and their master regulator, HSF1 contribute to tumor survival and metastatic dissemination." (PMID 31652993, 2019). "Since we found that Arc/Arg3.1 overexpression inhibits HSF1 transcriptional activities, we can suggest that Arc/Arg3.1 can be employed as a negative regulator of HSF1 in cancer treatment." (PMID 30796345, 2019). "Currently, several HSF1 inhibitors have been identified for the treatment of cancer, although the therapeutic effects are still being evaluated." (PMID 31878360, 2019). "In highly malignant human cancer cell lines, HSF1 activates genes involved in cell adhesion and migration." (PMID 31752429, 2019). "Studies have shown that HSF1 plays an important role in cancer cell tumorigenesis, apoptosis, and proliferation and multi-drug resistant in malignant tumors." (PMID 31878360, 2019).
cancer (continued). "Heat Shock Factor 1 (HSF1) is a key regulator of gene expression during acute environmental stress that enables the cell survival, which is also involved in different cancer-related processes." (PMID 31614463, 2019). "Heat shock transcription factor 1 (HSF1) is a master regulator of all heat shock responses and overexpressed in various cancers." (PMID 31878360, 2019). "In turn, HSF1 affects signalling to cancer cells promoting tumour growth whereas YAP promotes cancer cell invasion and angiogenesis through remodelling of the ECM." (PMID 30631061, 2019). "Using 10,287 cancer genomes from The Cancer Genome Atlas and Cbioportal databases, we assessed the association of HSF1 expression with CNA and cancer prognosis." (PMID 31699156, 2019). "Multiple pro-cancer activities of HSF1 and HSP upregulation urged researchers to establish inhibitors." (PMID 31652993, 2019). "In this context, Hsf1 regulates the expression of genes in human cancer cells required for metabolism, the cell cycle and translation." (PMID 29979776, 2018). "Heat shock factor 1 (HSF1) initiates a broad transcriptional response to proteotoxic stress while also mediating a cancer-specific transcriptional program." (PMID 29725069, 2018). "HSF1 is a 57 kDa cytoplasmic protein whose overexpression is related to increased malignancy and mortality in many cancer types, including breast, prostate, lung, kidney, and pancreas cancers." (PMID 30356024, 2018). "Our data therefore indicate that the relative disturbance in endogenous proteotoxic stress differs in different cancers and is reflected in the basal activity of HSF1, a main regulator of chaperone expression." (PMID 30138434, 2018). "In this review, we will first introduce the structure and role of HSF1 in cancer, with an emphasis on its transcriptional potential with compensatory role to sustain tumor cell survival and growth during heat shock." (PMID 30356024, 2018). "Connecting processes at the PN level, this evidence suggests a connection between TRiC/CCT and HSF1 stress response signalling also in cancers." (PMID 29293508, 2018). "In a joint model with the clinical Cancer of the Prostate Risk Assessment post-Surgical (CAPRA-S) score, nuclear HSF1 remained a predictive factor of shortened disease-specific survival." (PMID 30131848, 2018). "For example, resveratrol, a phenolic compound, found in grape seed, inhibits Akt phosphorylation to suppress HSF-1 activation in cancer cells, so that the efficacy is increased." (PMID 29682483, 2018). "Heat shock factor 1 (HSF1) has been identified as a promising drug target because it regulates several pathways responsible for cancer cell growth, metastasis, and survival." (PMID 30356024, 2018). "It is a potential opportunity for phytochemists to discover and isolate natural product(s) as a reliable inhibitor of HSF-1 to improve the lives of cancer patients." (PMID 29682483, 2018). "The transcriptional regulator HSF1 has been reported to not only be critical to sustain cancer proliferation, but also up-regulate a subset of genes exclusively in patient-derived malignant cell specimens that are distinct from the canonical HSR targets." (PMID 30111611, 2018). "HSF-1 is often constitutively active in cancer cells and plays a multifaceted role in malignant transformation, including atypical expression of HSPs." (PMID 29423046, 2018). "Recently, compounds that directly bind to and inhibit HSF1 have been reported; some of them were also found to be toxic for several cancer cell lines." (PMID 29930764, 2018). "Strikingly, intermediate or strong HSF1 nuclear expression was detected in the vast majority (93%) of the advanced cancer cores, and all except one of the cores simultaneously showed positive cytoplasmic HSF1 staining." (PMID 30131848, 2018). "The significance of HSF1 gene in cancer development is becoming apparent since it influences expression of HSPs, tumor suppressor genes, oncogenes, signal transduction and metabolism of glucose." (PMID 29494616, 2018).
cancer (continued). "HSF1 also promotes a cancer-specific transcriptional program that supports malignancy through the expression of genes for proliferation, anabolic metabolism, metastasis and apoptosis prevention." (PMID 29725069, 2018). "Hsp90 inhibitors have been shown to activate HSF1-mediated heat shock response, which in the long run protects cancer cells from apoptosis." (PMID 29799521, 2018). "Activation of HSF-1 is not only involved in carcinogenesis but it also enhances cancer cell survival post-chemotherapy or radiotherapy." (PMID 29682483, 2018). "In conclusion, our data show that assessment of endogenous proteotoxic stress, measured by endogenous HSF1 activity serves as a marker of cancer cell sensitivity to Hsp90 inhibition." (PMID 30138434, 2018). "The HSF1 expression was investigated using immunohistochemistry on FFPE tissues (cancer tissue and adjacent normal tissue)." (PMID 29494616, 2018). "The resulting tree revealed that while grade group remained the most informative prognostic factor (node 1), nuclear HSF1 expression status added to the survival prediction for advanced cancers (node 5)." (PMID 30131848, 2018). "Emerging evidence demonstrates that HSF1 is upregulated in human malignant tumours and acts as an oncogene to regulate tumour carcinogenesis and progression." (PMID 30326922, 2018). "In cancer, HSF1 enables malignant cell growth, is overexpressed in a number of tumor types, and is associated with poor prognosis." (PMID 29725069, 2018). "HSF-1 indeed has been reported to drive a transcriptional program in cancer cells, which is distinct from its conventional response to heat stress." (PMID 29682483, 2018). "Not surprisingly, HSF1 expression has been found to be elevated in various cancer cell lines and cancer types and HSF1 identified as a driver of carcinogenesis." (PMID 30131848, 2018). "In the recent years, considerable interest has been directed to the role of HSF1 in cancer development." (PMID 29494616, 2018). "To elucidate the role of the HSF1-CanSig in cancer, we mined and analyzed the overexpression in 9241 cancer cases from 27 unique primary tumor sites from The Cancer Genome Atlas (TCGA) hosted in cBioPortal." (PMID 29268782, 2017). "Our results confirm the unique role of chromosome 8q mediated by the master regulator HSF1 in cancer cases." (PMID 29268782, 2017). "HSF-1 is reported to promote cancer cell survival and enhanced chemotherapy resistance through autophagy." (PMID 29348836, 2017). "The intriguing link between the mRNA splicing machinery and the heat shock response and the important roles of both SF3B1 and HSF1 in cancer prompted us to further analyze the connections between SF3B1 and the HSR." (PMID 28445500, 2017). "By utilizing expression data from 9241 cancer patients, we identified that human chromosome 8q21-24 is a location hotspot for the most frequently overexpressed HSF1-CanSig genes." (PMID 29268782, 2017). "Considering the many functions of mTOR, such as sensing metabolic changes, these results and studies implicate HSF1 in many functions of cancer cell biology and a significant interplay between PI3K/AKT signaling, mTOR signaling, and HSF1 activity." (PMID 29088759, 2017). "Identified by Mendillo, Santagata, and coworkers, the HSF1 Cancer Signature (HSF1-CanSig) is a set of 475 genes overexpressed in a number of highly malignant cancer cells and primary tumors." (PMID 29268782, 2017). "Studies indicate HSF1 as a desirable target for inhibiting the stress response in cancer cells and therefore enhance the cell sensitivity to other stimuli, including hyperthermia, chemotherapy, and heavy metals." (PMID 28257109, 2017). "Intriguingly, the strength of the HSF1 cancer program correlates with the number of overexpressed HSF1-CanSig genes in 8q, illuminating the essential role of HSF1 in mediating gene expression in different cancers." (PMID 29268782, 2017).
cancer (continued). "In particular, a class of translation initiation inhibitors, known as rocaglates, has been proven to be extremely effective in suppressing HSF1 activity and to strongly constrain the growth of multiple cancer cell lines." (PMID 28903330, 2017). "In accordance with this assumption, many human tumor types and cancer cell lines express HSF1 constitutively at elevated levels." (PMID 28903330, 2017). "We observed that this HSF1-driven chromosome 8q gene is set to be overexpressed in a majority of cancer types." (PMID 29268782, 2017). "Yet another potential issue with HSF1 activators is that HSF1 promotes tumorigenesis and is activated in a broad range of highly malignant human cancers." (PMID 28293421, 2017). "These compelling evidences expand our understanding by revealing the importance of HSF-1 in autophagy regulation, which have likely significance in cancer research." (PMID 29348836, 2017). "How does the cell establish the typically constant level of HSF1 concentration and how is this regulation subverted during cancer?" (PMID 28445500, 2017). "A previous report showed that the interaction between HSF1 and Fbxw7 is diminished with HSF1 S303A and/or S307A mutants in cancer cells." (PMID 28194040, 2017). "We have undertaken a cancer bioinformatics approach to study the clustering of HSF1-CanSig genes in chromosome 8q." (PMID 29268782, 2017). "As well, correlations between high expression of HSF1 mRNA with cancer grade, metastasis, and poor prognosis suggest that it has a role in tumor progression." (PMID 28257109, 2017). "HSF1 (heat shock factor 1) is a transcription factor that is found to facilitate malignant cancer development and proliferation." (PMID 29268782, 2017). "Statistical modeling, hierarchical clustering, and gene ontology-based pathway analyses indicate crosstalk between HSF1-mediated responses and pre-mRNA 3′ processing in cancers." (PMID 29268782, 2017). "Therefore, we propose that SF3B1 mutations could be driving increased HSF1 levels in some cancers." (PMID 28445500, 2017). "In cancer cells, HSF1 mediates a set of genes distinct from heat shock that contributes to malignancy." (PMID 29268782, 2017). "Quercetin, a bioflavonoid compound, has been shown to have anti-tumor activities via targeting the HSF1-dependent HSPs in many cancer cell lines." (PMID 28914774, 2017). "As the larger role of HSF1 in cancer comes into focus, it is becoming clear HSF1 has a multitude of functions and promotes malignancy." (PMID 29088759, 2017). "In the present study, we show that the natural diterpenoid compound oridonin, which acts through posing oxidative stress in cancer cells, activates HSF1 and HSP70 and targets BCR-ABL for ubiquitin-proteasome degradation." (PMID 28128329, 2017). "Mechanistically, oridonin poses oxidative stress in cancer cells and directly binds to cysteines of HSF1, leading to the activation of this master regulator of the chaperone system." (PMID 28128329, 2017). "As a master regulator of all heat shock responses, heat shock transcription factor 1 (HSF1) is also overexpressed in a variety of cancers playing multifaceted roles." (PMID 28914774, 2017). "Based on the TCGA expression data obtained from cancer cases, we found that HSF1-CanSig genes are clustered at chromosome 8q substantiated by compelling statistical evidence under two null models: all protein-coding genes and all HSF1-CanSig genes." (PMID 29268782, 2017). "We devised an overexpression score to quantify the prevalence of HSF1-CanSig genes being overexpressed among cancer cases (see the “Materials and methods” section for details)." (PMID 29268782, 2017). "In contrast, when the rank of HSF1 is greater than the cutoff rank ~ 102, more diverse overexpression patterns are observed among HSF1-CanSig 8q genes, implying the diminishing control of HSF1 in those cancers." (PMID 29268782, 2017). "We selected 1682 cancer cases with HSF1 overexpressed two or more standard deviations above the reference." (PMID 29268782, 2017).